PKD2 (polycystin 2, transient receptor potential cation channel)
Diseases named in the same sentence as PKD2 in open-access papers (continued):
Sharing a sentence is not in itself a finding about the gene and the disease.
Obesity (3 papers, 2021 to 2025). Accumulation of substantial excess body fat. "Altogether, these findings indicate that inactivation of PKD2 protects from diet‐induced obesity as well as associated hyperglycemia and hyperlipidemia." (PMID 33949105, 2021). "Importantly, we verified that the inhibition of PKD2 might be a valid strategy for the treatment of obesity and associated diseases in the future." (PMID 33949105, 2021). "Altogether, these findings suggest that PKD2 promotes obesity by increasing the capacity of the organism to absorb fat from the calories‐dense HFD." (PMID 33949105, 2021). "Taken together, deletion of PKD2 specifically in the intestine is sufficient to limit lipid absorption from consumed food and protect against diet‐induced obesity and glucose intolerance." (PMID 33949105, 2021). "Targeting PKD2, genetically or with small molecule inhibitors, reduces triglycerides absorption and prevents the development of obesity in mice and presumably in humans." (PMID 33949105, 2021). "In addition, PKD2 inactivation has been shown to limit intestinal lipid absorption, thereby protecting against diet-induced obesity." (PMID 41349796, 2025). "Our data suggest that pharmacological inhibition of PKD2 might restrict lipid uptake in the intestine and mitigate diet‐induced obesity." (PMID 33949105, 2021). "Consistently with these results, the ablation of PKD2 activity or the specific deletion of this kinase in the intestine resulted in reduced absorption of fat, increased excretion of energy in the feces and resistance to high‐fat diet‐induced obesity." (PMID 33949105, 2021). "As indicated by our data, inhibition of PKDs (especially PKD2) in the intestine might be an attractive strategy to ameliorate obesity in humans." (PMID 33949105, 2021). "Although PKD inhibition did not evoke any obvious adverse effects in mice, the development of drugs targeting PKD2 only might increase the safety of the potential anti‐obesity therapy." (PMID 33949105, 2021). "Therefore, we establish PKD2 as a key component of the intestinal fat absorption and an attractive target for future anti‐obesity therapies." (PMID 33949105, 2021). "Taken together, our findings suggest that PKD2 represents a key signaling node promoting dietary fat absorption and may serve as an attractive target for the treatment of obesity." (PMID 33949105, 2021). "Next, we tested whether inhibition of PKD2 could be used to ameliorate previously established obesity." (PMID 33949105, 2021). "Moreover, in line with the previous results from mice missing PKD2 activity globally, deletion of PKD2 specifically in the intestine resulted in resistance to HFD‐induced obesity and body fat accumulation and improved glucose tolerance." (PMID 33949105, 2021).
Osteopenia (3 papers, 2012 to 2021). Osteopenia is a term to define bone density that is not normal but also not as low as osteoporosis. "We found that loss of Pkd2 suppressed both osteoblast-mediated bone formation and adipogenesis, leading to osteopenia and decreased bone marrow fat." (PMID 25464512, 2014). "Thus, selective Pkd2 deficiency causes a low turnover osteopenia." (PMID 25464512, 2014). "Meanwhile, pkd2 inactivation specifically in mature mouse osteoblasts leads to osteopenia and these mice exhibit reduced expression of several osteoblast-specific genes markers." (PMID 33919210, 2021).
cardiac hypertrophy (2 papers, 2018 to 2021). "The increase in the extracellular matrix in Pkd2-KO myocardium led to cardiac hypertrophy, interstitial and conduction system fibrosis, causing cardiac dysfunction with a predisposition to arrhythmia." (PMID 34901233, 2021). "Interestingly, PKD1's closely related relatives PKD2 and PKD3 have also been implicated in the regulation of cardiac glucose uptake and cardiac hypertrophy, together resulting in a complex signaling network." (PMID 29930945, 2018). "Hence, the role of PKD2 in the development of cardiac hypertrophy in db/db mice awaits further investigations." (PMID 29930945, 2018).
channelopathies (2 papers, 2016 to 2025). "Since ADPKD is considered a renal ciliopathy–channelopathy, and because ciliary exclusion of PKD2 promotes kidney cystogenesis, our results were obtained from a purposefully designed experiment that assesses channel trafficking and functional defects in their near-physiological context (51, –53)." (PMID 40504156, 2025).
congenital heart disease (2 papers, 2023 to 2024). A heart disease that is present at birth. "PKD2 is currently thought to act as a mechanical sensor in regulating the asymmetric development of the left and right organs, and its mutation can lead to congenital heart disease." (PMID 39451240, 2024). "Moreover, patients with mutations in PKD1L1 or in PKD2 present laterality phenotypes such as situs inversus, heterotaxia and congenital heart disease." (PMID 37477290, 2023). "Therefore, the development of related molecular drugs to treat congenital heart disease induced by PKD2 dysfunction is also an important direction in the future." (PMID 39451240, 2024).
depression (2 papers, 2016 to 2025). "This network consisted of a number of molecules previously reported to be associated with depression (according to a PubMed search), such as CYP3A5, VAMP2, CSGALNACT1, CASP8, CRHR2, PKD2, and OXT." (PMID 26728011, 2016). "In addition, FKBP4, PKD2, CSGALNACT1, and VAMP2 have been reported in relation to depression (or mood disorders)." (PMID 26728011, 2016).
diabetic cardiomyopathy (2 papers, 2015 to 2018). Diabetic cardiomyopathy is a disorder of the heart muscle in people with diabetes. "In conclusion, here we showed that the 8 week old db/db mouse is a model of developing diabetic cardiomyopathy characterised by diastolic and systolic dysfunction, but not pathological hypertrophy, and PKD2 activation in the fed state." (PMID 25798941, 2015). "Moreover, PKD2, but not PKD1, auto-phosphorylation is upregulated in hearts of db/db mice, a mouse model of diabetic cardiomyopathy." (PMID 29930945, 2018).
dyslipidemia (2 papers, 2019 to 2025). "For example, MUC1, SLC2A9, GCKR, and PKD2 may influence other metabolic syndrome–related traits such as blood pressure and FG." (PMID 31408958, 2019).
idiopathic dilated cardiomyopathy (2 papers, 2016 to 2023). Decreased function of the heart associated with cardiac enlargement and congestive heart failure, of unknown cause. "Over the past few years, several new proteins have been implicated as causative of idiopathic dilated cardiomyopathy and the results presented here show that Pkd2 should be added to the list." (PMID 27081851, 2016).
invasive ductal carcinoma (2 papers, 2009 to 2015). "We analysed TMAs including 10 normal breast tissue samples, 40 invasive ductal carcinoma of the breast and 10 metastatic invasive ductal carcinoma samples from lymph nodes for the expression of the PKD family kinases, PKD1, PKD2 and PKD3." (PMID 19243594, 2009). "Similarly, the expression levels of PKD2, the kinase that phosphorylates VASP at this site, are decreased in invasive ductal carcinoma samples of all three groups." (PMID 26336132, 2015).
left ventricular hypertrophy (2 papers, 2016 to 2025). Enlargement of the LEFT VENTRICLE of the heart. "Intriguingly, the Pkd2+/- 5 mo mice did not present with a cardiac phenotype that paralleled either dilated cardiomyopathy or left ventricular hypertrophy, and had preserved ejection fraction." (PMID 27081851, 2016).
liver cancer (2 papers, 2016 to 2023). An epithelial or non-epithelial malignant neoplasm that arises from the liver. "The percentage of p-PKD2-positively stained cells increased from 18% for normal liver to 57% for liver cancer, and this difference was highly significant." (PMID 26683365, 2016).
male infertility (2 papers, 2022 to 2025). The inability of the male to effect fertilization of an ovum after a specified period of unprotected intercourse. "Some studies have found that PDK2 dysfunction often leads to male infertility and human reproductive defects, indicating that PKD2 plays an important role in the reproductive system." (PMID 39958158, 2025). "Hence, silencing of the PKD2 ortholog, of which the expression is enriched in male reproductive organs, was shown to induce male infertility due to the inability of the spermatozoa to correctly find their way through the female genital tract and reach the sperm storage organs of the female flies." (PMID 35409285, 2022).
Marfan syndrome (2 papers, 2025). A disorder of the connective tissue. "Each of these disorders has well-established major causative genes: PKD1 and PKD2 for ADPKD, FBN1 for Marfan syndrome, and NF1 for NF1 disease." (PMID 41411243, 2025). "Causative genes include autosomal polycystic kidney disease (PKD1, PKD2), Ehlers–Danlos syndrome (COL3A1), Marfan syndrome (FBN1), Loeys–Dietz syndrome (TGFB2, TGFB3, TGFBR1, TGFBR2, SMAD2, SMAD3), and Majewski Osteodysplastic Primordial Dwarfism (PCNT)." (PMID 40004483, 2025).
Pancreatic cysts (2 papers, 2024). A cyst of the pancreas that possess a lining of mucous epithelium. "First, the presence of pancreatic cysts, 2 mm or larger, predicts the greater likelihood of the PKD2 over the PKD1 mutation." (PMID 39058059, 2024).
Sepsis (2 papers, 2018 to 2023). Sepsis is defined as life-threatening organ dysfunction caused by a dysregulated host response to infection. "Further, treatment with the specific PKCδ inhibitor decreased PKD2 phosphorylation as well as platelet p-selectin expression indicating a direct effect on platelets in this sepsis model." (PMID 29617417, 2018). "However, in this paper we demonstrate a direct effect on platelets, as we show that sepsis induced platelet PKD2 phosphorylation, a known substrate of PKCδ in platelets." (PMID 29617417, 2018).
acute lung injury (1 paper, 2023). A condition of lung damage that is characterized by bilateral pulmonary infiltrates (pulmonary edema) rich in neutrophils, and in the absence of clinical heart failure. "Polycystin-2 (PC2), which is a transmembrane protein encoded by the PKD2 gene, plays an important role in kidney disease, but its role in lipopolysaccharide (LPS)-induced acute lung injury (ALI) is unclear." (PMID 37198573, 2023).
aneurysm (1 paper, 2022). Bulging or ballooning in an area of an artery secondary to arterial wall weakening. "Significantly, in the subgroup of patients who experienced aneurysms, 10 (58.8%) patients had a non-truncant PKD1 mutation, 3 (17.6%) had a truncant PKD1 mutation, 1 (5.9%) carried a different mutation from PKD1 or PKD2, and the genetic analysis of 3 (17.6%) was unavailable." (PMID 34586427, 2022).
Aortic dissection (1 paper, 2025). Aortic dissection refers to a tear in the intimal layer of the aorta causing a separation between the intima and the medial layers of the aorta. "Therefore, PKD1 and PKD2 gene abnormalities alone may not fully explain the increased risk of aortic dissection in PKD, warranting further investigation." (PMID 40093803, 2025).
Arrhythmia (1 paper, 2021). Any cardiac rhythm other than the normal sinus rhythm. "While no apparent arrhythmia was observed in the Pkd2-KO mouse model in vivo, the Pkd2-KO hearts were susceptible to arrhythmia when hearts were isolated away from neuronal input in the ex vivo studies." (PMID 34901233, 2021). "Cardiac arrhythmia was also evidence in Pkd2-KO hearts at higher preloads." (PMID 34901233, 2021). "The Pkd2-KO hearts showed a scarring process and cardiac muscle fibrosis with the fatty fibrotic changes in the sinoatrial node (SAN), which could serve as the underlying risk factor for cardiac arrhythmia in PKD patients." (PMID 34901233, 2021).
asthenozoospermia (1 paper, 2022). "The authors analyzed a set of 90 unrelated families with ADPKD and identified predicted pathogenic variants in PKD1 and PKD2 associated with low sperm quality, mainly asthenozoospermia or oligo-astheno-zoospermia." (PMID 35409285, 2022).
astrocytic tumor (1 paper, 2025). A glial tumor of the brain or spinal cord showing astrocytic differentiation. "The aim of the present research study was to investigate the expression of PKD1 and PKD2 in astrocytic tumors and correlate it with clinicopathological characteristics such as the grade of malignancy, age, and gender of the patients." (PMID 40299470, 2025).
astrocytomas (1 paper, 2025). "Spearman’s correlation analysis revealed a significant relationship between PKD1 and PKD2 expression in astrocytomas included in the study (rho = 0.629, p = 0.01)." (PMID 40299470, 2025). "In the present study, we aimed to investigate the expression of PKD1 and PKD2 and their encoded proteins PC1 and PC2 in astrocytoma samples including GBMs." (PMID 40299470, 2025). "Gene expression analysis by qRT-PCR revealed significantly increased levels of PKD1 and PKD2 in astrocytomas compared to normal brain tissues (p < 0.05)." (PMID 40299470, 2025). "Both PC1 and PC2 (and their counterpart genes, PKD1 and PKD2) demonstrated significantly increased expression throughout the astrocytoma tissues compared to the normal brain samples." (PMID 40299470, 2025). "In this aspect, the expression of PKD1 and PKD2 in human astrocytomas is largely unknown." (PMID 40299470, 2025). "PKD2 expression was significantly higher in WHO, grade IV astrocytomas as compared with WHO, grade II astrocytomas and WHO, grade III astrocytomas (p < 0.05)." (PMID 40299470, 2025). "The aim of the present study was to investigate the expression of PKD1 and PKD2 as well as PC1 and PC2 in serial sections of different grades of malignancy astrocytoma samples and compare them with normal brain tissues." (PMID 40299470, 2025).
atrial fibrillation (1 paper, 2021). A disorder characterized by an electrocardiographic finding of a supraventricular arrhythmia characterized by the replacement of consistent P waves by rapid oscillations or fibrillatory waves that vary in size, shape and timing and are accompanied by an irregular ventricular response. "Atrial fibrillation (AF) or AV block was seen in isolated Pkd2-KO hearts." (PMID 34901233, 2021). "Without neurohumoral effects, WT hearts showed a regular rhythm with 125 ± 20 beats per minute, and the Pkd2-KO hearts had arrhythmic heart rate of 127 ± 22 beats per minute evidence from atrial fibrillation or atrioventricular block characterized by irregular R-R intervals." (PMID 34901233, 2021).
bladder urothelial carcinoma (1 paper, 2025). "In the bladder urothelial carcinoma (BLCA) protein-protein interaction network, the number of nodes was 118, and the number of edges was 108 (cutoff: 0.46), and PRKD1 gene had direct interaction with PKD1 and PKD2." (PMID 40984898, 2025).
chronic myeloid leukemia (1 paper, 2014). "Similarly, PKD2 was reported to mediate the activation of NF-κB pathway in chronic myeloid leukemia cells." (PMID 25136641, 2014).
colitis (1 paper, 2016). Inflammation of the colon. "Together, these data indicated that PKD2 catalytic activity deficiency is detrimental to the development of DSS-induced colitis in mice." (PMID 27659202, 2016). "Surprisingly, our findings revealed that PKD2 enzymatic deficiency increased susceptibility of mice to DSS-induced colitis." (PMID 27659202, 2016). "In the present study, we showed that PKD2 enzymatic deficiency mice exhibit elevated susceptibility to dextran sulfate sodium (DSS)-induced colitis compared with wild-type control, up-regulated expression of crucial pro-inflammatory cytokines and disrupted epithelial barrier function." (PMID 27659202, 2016). "More importantly, our findings provide unequivocal genetic evidence in vitro and in vivo that PKD2 protects against DSS-induced colitis by regulating inflammation and epithelial barrier function." (PMID 27659202, 2016). "In summary, our present studies demonstrate for the first time that PKD2 exerts a protective effect on experimental colitis, highlighting the relevance of PKD2 as a potential therapeutic molecule to treat IBD." (PMID 27659202, 2016). "Based on these findings, we investigated the role of PKD2 in IBD with DSS-induced murine colitis model, which resembled human IBD in the aspect of barrier dysfunction and inflammatory response." (PMID 27659202, 2016). "Colitis was induced in wild-type mice (PKD2WT/WT) and PKD2 catalytic activity deficient mice (PKD2SSAA/SSAA) with dextran sulfate sodium." (PMID 27659202, 2016). "Additionally, the expression levels of serum IgA and IgG also showed no change between the four groups, suggesting that PKD2 enzymatic deficiency had little effect on the function of B-cell subtypes in acute DSS-induced colitis." (PMID 27659202, 2016). "The present study was to define PKD2 might affect murine colitis." (PMID 27659202, 2016). "To assess the role of PKD2 in epithelial barrier function, we first analyzed the expression of ZO-1 and MUC2 in colon of mice with DSS-induced colitis." (PMID 27659202, 2016).
dental caries (1 paper, 2021). The decay of a tooth, in which it becomes softened, discolored, and/or porous. "PKD2 gene is one of the genes that has been associated with dental caries and had an implication in craniofacial development and mutation in PKD2 has been linked to craniofacial anomalies and tooth loose in mice." (PMID 34311721, 2021).
diabetic neuropathy (1 paper, 2018). A chronic, pathological complication associated with diabetes mellitus, where nerve damages are incurred due to diabetic microvascular injury involving small blood vessels that supply these nerves, resulting in peripheral and/or autonomic nerve dysfunction. "We assessed changes in gene expression of sorbitol dehydrogenase (SORD) and aldose reductase (AKR1B1) as an indirect measure of polyol pathway flux and, along with protein kinase C (PKD2), as key characteristic markers for diabetic neuropathy." (PMID 30470798, 2018).
dilated cardiomyopathy (1 paper, 2016). Cardiomyopathy which is characterized by dilation and contractile dysfunction of the left and right ventricles. "Anatomically, the 9 month old Pkd2+/- mice had thinner left ventricular walls, consistent with dilated cardiomyopathy, and the left ventricular ejection fraction was decreased." (PMID 27081851, 2016). "These anatomical data are all consistent with a progressive dilated cardiomyopathy phenotype in the 9 mo Pkd2+/- mice." (PMID 27081851, 2016). "Importantly, we find that the Pkd2+/- mice mimic a phenotype that has more similarities to dilated cardiomyopathy than hypertrophic cardiac myopathy." (PMID 27081851, 2016).
dyslexia (1 paper, 2016). A learning disorder characterized by an impairment in processing written words. "PKD2 gene was reported as a risk locus for handedness and brain asymmetry that have been linked to neurodevelopmental disorders such as dyslexia." (PMID 27450446, 2016).
endometrial cancer (1 paper, 2022). Primary or metastatic malignant neoplasm involving the endometrium (mucous membrane that lines the endometrial cavity). "High levels of PKD2 in endometrial cancer may also be associated with a significant decrease in miR-134 activity in G2 and G3 cancer." (PMID 36555458, 2022). "The obtained results indicate that overexpression of PKD2 may be related to significantly reduced activity of miR-195-3p, miR-20a and increased the levels of miR-106a, miR-328 in the early stages of endometrial cancer." (PMID 36555458, 2022). "High levels of miR-106a in G1 endometrial cancer and overexpression of PKD2 may indicate that the potential regulation of expression does not occur directly, and perhaps the activity of elements modulating the normal level of PKD2 is suppressed." (PMID 36555458, 2022). "The obtained results indicate the overexpression of PRDX2 and PKD2 in endometrial cancer, regardless of its grade, which is consistent with the analysis at the mRNA level." (PMID 36555458, 2022).